ABCB5 (ATP binding cassette subfamily B member 5)
Diseases named in the same sentence as ABCB5 in open-access papers (continued):
Sharing a sentence is not in itself a finding about the gene and the disease.
melanoma (continued). "Interestingly, Kleffel and coworkers have recently shown that a variable and usually small proportion of melanoma cells express the PD-1 receptor on their surface; interestingly, the majority of PD-1+ cells co-express ABCB5." (PMID 29156643, 2017). "Immunohistochemical analyses have shown that CD133+ and ABCB5+ subpopulations are co-localized in human melanomas at the level of perivascular niches that contain VE-cadherin-positive melanoma cells forming vessel-like channels—a phenomenon called vascular mimicry." (PMID 29156643, 2017). "Furthermore, ABCB5+ melanoma cells inhibit T-cell activation through IL-2 and induce CD4+CD25+FoxP3+ regulatory T (Treg) cells via B7.2 dependent manner." (PMID 28137308, 2017). "In addition, ABCB5 has been found to be involved in self-renewal, differentiation and melanoma progression." (PMID 28677036, 2017). "Additionally, recent clinical data showed that there were significant increase in the number of ABCB5+CD271+RANK+ CSCs in circulatory tumor cells (CTCs) at late stage of melanoma." (PMID 28137308, 2017). "In addition, we found that expression of the ΔNp73 isoform p73ΔEx2/3 correlates with ABCB5 expression in metastases from melanoma patients and in melanoma-derived cells." (PMID 28677036, 2017). "In addition, ABCB5+ melanoma cells showed tumor initiation at the level of 1x105 cells, whereas 100-fold more ABCB5− cells are required to develop tumor under in vivo condition indicating the importance of CSCs in melanoma progression." (PMID 28137308, 2017). "Finally, a very recent study showed that melanoma chemotherapy leads to the selection of ABCB5-expressing cells." (PMID 29156643, 2017). "Additionally, combined treatment with engineered VNP20009, carrying shABCB5 and Cyclophosphomide (CTX) drastically reduced ABCB5+ CSCs that leads to attenuation of melanoma tumor growth and enhanced survival time." (PMID 28137308, 2017). "Furthermore, ABCB5, a marker of skin progenitor cells and malignant melanoma initiating cells (MMIC), functions as a regulator of cellular differentiation." (PMID 29117122, 2017). "In this study, it evidence was also provided that there is a positive correlation between ABCB5 immunoreactivity and the clinical evolution of melanoma: in fact, ABCB5 expression was higher in primary melanoma than nevus and lymph node metastasis than primary melanoma." (PMID 29156643, 2017). "A recent study provided evidence that ABCB5 might provide a functional link between melanoma-initiating cell maintenance, multi-drug resistance, and tumor growth in malignant melanoma." (PMID 29156643, 2017). "Drug-resistant metastatic melanoma cells tend to be ABCB5 enriched and may show tumor re-growth after dacarbazine, temozolomide or vemurafenib treatment." (PMID 28677036, 2017). "Moreover, Honokiol (HNK), a biphenolic natural compound reduces the expression of various stem cell markers such as CD271, CD166, JARID1B and ABCB5 in melanoma." (PMID 28137308, 2017). "ABCB5 was first identified as a regulator of membrane potential and cellular fusion and has also been shown to serve as a marker for limbal stem cells, skin progenitor cells and melanoma stem cells, suggesting a role in maintaining stemness." (PMID 28677036, 2017). "In addition, previous studies found that ABCB5 was expressed in skin progenitor cells and melanoma stem cells, and functioned as a regulator of cellular differentiation." (PMID 29116027, 2017). "In addition to VEGF-R1, also RANK (receptor activator of NF-kB) has been shown to be expressed on ABCB5+ melanoma-initiating cells, thus suggesting a possible role of this receptor in maintaining melanoma CSCs." (PMID 29156643, 2017). "In addition to these markers, ABCB5+ melanoma cells also express VEGF-R1, which plays a role in the control of the proliferation and vasculogenic mimicry of these cells." (PMID 29156643, 2017).
melanoma (continued). "In addition to low levels of MITF, different markers, including ABCB5 and JARID1B, have been associated with the generation of melanoma‐initiating cells." (PMID 27596438, 2016). "Based on metabolite profiles acquired for extracts of ABCB5-WT and ABCB5-KD G3361 melanoma cells, 45 metabolite concentrations were obtained for each sample group (see Figures A-C in S1 File for representative metabolite spectra for extracts of ABCB5-expressing G3361 cells)." (PMID 27560924, 2016). "Both CD133 and ABCB5 have been identified as CSC markers of human melanoma." (PMID 26910836, 2016). "Furthermore, ABCB5 is frequently correlated with the in vitro clonogenic potential of melanoma cells." (PMID 26910836, 2016). "ABCB5 has also been identified as a CSC marker in human melanoma." (PMID 26910836, 2016). "Overall, these data suggest ABCB5 as a CSC marker of murine melanoma." (PMID 26910836, 2016). "Thus inhibition of ABCB5 can reverse the resistance of B16F10 melanoma cells to paclitaxel and doxorubicin." (PMID 26910836, 2016). "A gain-of-function in the melanoma stem cell marker ABCB5 is also probable because of its connection with five down-regulated UV-miRNAs, and two of them (miR-186-5p/186 and miR-331-3p) are identical to the ones that are up-regulated in the irradiated melanocytes of healthy persons." (PMID 27149382, 2016). "Our results indicate overall higher levels of water-soluble metabolites due to expression of ABCB5 in normoxic G3361 melanoma cells, notably for several compounds involved in glycolysis and phospholipid metabolism, but also for some organic acids, such as amino acids." (PMID 27560924, 2016). "Thus, both glycolysis and PL metabolism appear to be primed for growth by ABCB5 expression in G3361 melanoma cells." (PMID 27560924, 2016). "Significant differences between phospholipid levels in ABCB5-WT and ABCB5-KD G3361 melanoma cells." (PMID 27560924, 2016). "ABCB5 has also been reported to be expressed in human melanoma tumor-initiating cells." (PMID 26666373, 2015). "For instance, malignant melanoma stem cells express the ATP-binding cassette transporter ABCB5 which plays an important role in drugs efflux, and, thereby, may attenuate the therapeutic efficiency of the inhibitors used in cancer therapy." (PMID 26404379, 2015). "ABCB5 is closely related to P-gp and confers doxorubicin resistance in malignant melanoma." (PMID 26617519, 2015). "Also, ABCB5 has been found at the surface of a subset of melanoma cells that exhibit enhanced tumor initiating cell phenotype." (PMID 25105565, 2014). "The impact on ABCB5-positive melanoma cells was quite different for two other drugs, maytansine and colchicine." (PMID 24595456, 2014). "Melanoma cells that express ABCB5 protein could selectively survive when exposed to dacarbazine, vemurafenib and other drugs." (PMID 24595456, 2014). "ABCB5 has been described as a marker for tumor-initiating cells in human melanoma." (PMID 24559071, 2014). "We cannot exclude that other cell surface markers like ABCB5 or transcription factors like SOX2 may participate or even act as critical factors in the transition of melanoma cells phenotype." (PMID 24799129, 2014). "Its high capacity to select ABCB5-positive and slow-cycling cells could however be used in in vitro experiments to enrich melanoma population with cells potentially exhibiting stem-cell characteristics." (PMID 24595456, 2014). "Interestingly, one of the multidrug transporters - ABCB5 -, has been put forward as a marker of melanoma CSC." (PMID 24098529, 2013). "ABCB5 has also been advanced as melanoma CSC marker by others." (PMID 24098529, 2013). "Interestingly, TNC has been reported to maintain an ABCB5+ subpopulations of melanoma-initiating cells thereby promoting melanoma progression." (PMID 22947174, 2012). "Here we explored the effect of anti-melanoma treatments on the ABCB5-expressing cells." (PMID 22675422, 2012).
melanoma (continued). "Moreover, the growth of melanoma xenografts in mice was delayed when the animals were treated with a monoclonal anti-ABCB5 antibody." (PMID 22675422, 2012). "Our results show that anti-melanoma chemotherapy might participate to the chemoresistance acquisition by selecting tumor cell subpopulations expressing ABCB5." (PMID 22675422, 2012). "Our results suggest that the couple WM-115/WM-266-4 tumor cell lines might be an interesting in vitro model to study the role of the ABCB5 protein and of ABCB5-expressing cells in melanoma aggressiveness." (PMID 22675422, 2012). "In the present work focused on melanoma, we show that ABCB5+ cells have a survival advantage over the bulk of tumor cells when they are exposed to different cytotoxic compounds, including drugs that are used in melanoma treatment." (PMID 22675422, 2012). "Nevertheless, the level of resistance of melanoma ABCB5-expressing cells to relevant chemotherapeutic drugs remains unknown." (PMID 22675422, 2012). "To assay the variation of the expression of ABCB5, we first devised the methodology to detect the presence of ABCB5-expressing cells in a panel of melanoma cell lines using a rabbit polyclonal antibody raised against a peptide derived from the ABCB5 protein sequence (ABCB5-AbRock)." (PMID 22675422, 2012). "Interestingly, it was previously shown that ABCB5 expression level is correlated with the grade of melanoma." (PMID 22675422, 2012). "While ABCB5+ cells were reported to define a CSC subpopulation in melanoma, their tumorigenic potential in HCC remained unknown." (PMID 22194816, 2011). "Moreover, the therapeutic effect of anti-proliferative drugs will be counteracted by the pronounced expression of the chemo-resistance mediator ABCB5 in melanoma CSCs." (PMID 21487158, 2011). "ABCB5 beta has important clinical implications, as it may be involved with multidrug resistance in melanoma stem cells, allowing these stem cells to survive chemotherapeutic regimes." (PMID 21298007, 2011). "However, the expression of CD24, CD44 and CD133 (or ABCB5) in melanoma B16 cells implies that CSC-like cells emerge during tumorigenesis." (PMID 20950440, 2010). "In 2009 Schatton and Frank proposed that CSCs in human melanoma that express the chemoresistance mediator ABCB5 might be responsible for melanoma immune evasion." (PMID 20459772, 2010). "ABCB5 expression in tumor cells correlates with clinical melanoma progression." (PMID 20459772, 2010). "Furthermore, high expression of ABCB5 was responsible for chemoresistance in melanoma cells." (PMID 40746888, 2025). "Circulating tumor cells (CTCs) enriched for ABCB5 exhibit distinct transcriptomic profiles, suggesting that ABCB5+ CTCs may have an invasive phenotype and play different roles in disease progression compared to other melanoma subpopulations." (PMID 40867277, 2025). "Notably, ABCB5 expression at mRNA and protein levels was increased in cell lines resistant to vemurafenib, a molecule targeting the BRAF-activating mutation V600E used in the treatment of melanoma." (PMID 39267923, 2024). "Similarly, the Wnt/IL-1β/IL-8 pathway was shown to induce ABCB5 expression in mesothelioma, and three signaling pathways, NF-κB, α6-β4-integrin, and IL-1, were overexpressed in ABCB5+ melanoma cells purified by immunomagnetic selection and abcam 140667 anti-ABCB5 antibody." (PMID 39267923, 2024). "Finally, T cell inhibition may be directly triggered by tumor cell-secreted cytokines, including IL-4, IL-10 and TGF-β; it has been reported that ABCB5+ melanoma cells express and release in the TME high levels of TGF-β-related factors." (PMID 39199632, 2024). "Although the literature is still controversial regarding the existence of CSCs in melanoma, the “phenotype switching” model is the most commonly used to explain tumorigenesis in recent publications on melanoma formation and progression, which calls into question the expression of ABCB5 in CSCs." (PMID 39267923, 2024).
melanoma (continued). "In addition, ABCB5 is the novel potential marker of melanocytes, which could promote melanoma metastasis by activating the NF-?B signaling pathway." (PMID 37273909, 2023). "Indeed, we and others found that commercial antibodies may be used to detect the overexpressed protein but fail to detect ABCB5 expressed endogenously in melanoma cells, at least by classical Western blotting and immunofluorescence methods." (PMID 37958830, 2023). "Regarding the expression of genes associated with cellular processes, melanoma aggressiveness, resistance and cell survival, a significant difference was found in the expression of ABCB5, CAV1 and S100A9 compared with the control (cells not exposed to the extract)." (PMID 36431795, 2022). "Furthermore, as ABCB5 was found expressed on melanoma cells, one might suspect that, if there indeed were melanoma cells present in the primary culture, sorting for ABCB5+ cells could even enrich them during the courses of cell expansion and isolation." (PMID 33741066, 2021). "Nevertheless, a variety of markers associated with some melanoma-specific cell-surface epitopes have been proposed, such as MCAM/MUC18/CD146 and MSCP/NG2 (melanoma-associated chondroitin sulfate), together with stem cell markers, such as ABCB5 (ATP-binging cassette subfamily member B) and CD271." (PMID 32548126, 2020). "Another functional driver of melanoma aggressiveness features through a common molecular role in tumor growth, maintenance, and drug resistance is exerted by the cell membrane-associated transporter ABCB5 (ATP-binding cassette sub-family B member 5, also known as P-glycoprotein)." (PMID 32548126, 2020). "In addition, 17-aminogeldanamycin significantly reduces c-MYC transcript level while not affecting the frequency of cells positive for ATP-binding cassette, sub-family B, member 5 (ABCB5), which is a drug efflux transporter that mediates chemoresistance and marks melanoma-initiating cells." (PMID 30989459, 2019). "ABCB5 may be associated with resistance in some but not all BRAF inhibitor-resistant melanoma cell lines." (PMID 29929490, 2018). "Thus, further molecular and functional studies aiming to investigate the role of ABCB5 in melanoma CTCs, and interrogate CTC phenotypes during disease evolution as well as throughout treatment will unveil the relationship between ABCB5 and melanoma progression." (PMID 28978038, 2017). "In addition, it has been reported that ABCB5 is expressed in human melanoma tumor-initiating cells." (PMID 26666373, 2015). "Although these cells acquired melanoma stem cell markers, including ABCB5 and CD271, and self-renewal ability, they lost their capacity to differentiate, as evidenced by the diminished MelanA expression in melanosphere cells and the loss of pigmentation in a skin equivalent model of human melanoma." (PMID 25223735, 2014). "Similarly, ABCB5, an ATP- dependant cassette transporter of various substrate such as small ions, sugars, peptides, and complex organic molecules, has been shown to confer doxorubicin resistance to melanoma cells." (PMID 25105565, 2014). "An added benefit of our method is that it enriched for a variety of melanoma CTCs; while it targets those detected by the CellSearch Kit (MCSP and MCAM positive), it also targets CTCs expressing melanoma initiating cell markers (ABCB5 and CD271), which might be excluded by other methods." (PMID 24915896, 2014). "Indeed, JARID1B-negative cells could become positive and ABCB5+ melanoma cells generate both ABCB5+ and ABCB5− progeny." (PMID 24416617, 2013). "Nevertheless the behaviour of the ABCB5+ subpopulation upon anti-melanoma drugs remains unknown." (PMID 22675422, 2012). "ID3 (inhibitor of differentiation) and ABCB5 (subfamily B, member 5) transporter (a member of the ATP-binding cassette (ABC) superfamily) overexpression is reported in VemR melanomas." (PMID 40558548, 2025).
melanoma (continued). "In melanoma, its expression is activated by Wnt/β-catenin and MITF, and as expected, ICG-001 treatment suppressed ABCB5 mRNA as well as expression of ABCB5 immunoreactive isoforms in both our VemR models." (PMID 40558548, 2025). "The authors showed that melanoma cell lines A375 and BLM share the expression of the stem cell markers ABCB5 and CD44, but A375 cells uniquely expressed CD271 and exhibited melanosphere formation, a hallmark of stemness, unlike BLM cells." (PMID 40867277, 2025). "The CD133+ and ABCB5+ MSLCs in perivascular niches, expressing VE-cadherin, TIE2, VEGF, and VEGFR, possess the ability to acquire the VM phenotype and contribute to melanoma drug resistance." (PMID 40399946, 2025). "Using an in vitro tumor sphere formation assay, we found that DHCR24 contributed to the proliferation of stem-like melanoma cell populations, and the stem cell property of the spheroids was confirmed by the expression of Sox2, CD133, Nanog and ABCB5." (PMID 38775844, 2024). "ABCB5 and CD133 were also co-expressed in clinical melanoma samples using immunofluorescence and 3C2-1D12 antibody." (PMID 39267923, 2024). "Consistently, it has been reported that ABCB5+ and CD271+ melanoma cells express very low levels of the differentiation marker MART-1 as well as of cancer–testis antigens." (PMID 39199632, 2024). "Accordingly, genes such as ABCB1, ABCB5, and ABCG2 undergo differential expression in both melanocytes and melanoma cells." (PMID 38275910, 2024). "ABCB5, a member of the ABC family of transporter proteins, is highly expressed in CD133(+) melanoma cells." (PMID 39611156, 2024). "For instance, the co-expression of MDR1, ABCB5 and ABCC2 was observed in a subpopulation of melanoma cells." (PMID 38004589, 2023). "CMCs isolation was based on immunomagnetic enrichment of CD45 depleted, about 99.98% of leukocytes are depleted, by virtue of melanoma-specific CD146/MCAM and ABCB5 antigen expression." (PMID 37511550, 2023). "Originally, ABCB5 was characterized on CD133+ human epidermal melanocyte progenitor cells, acting as a negative regulator of cell differentiation, and on human malignant melanoma cells, serving as a chemoresistance-conferring drug efflux transporter." (PMID 36613507, 2022). "Evidence has shown that ABCB5- and CD133-expressing cells are co-localised in the perivascular niche where vasculogenic mimicry takes place in melanoma xenografts." (PMID 35740696, 2022). "For this stage, there are several markers for melanoma-initiation, such as MAGE proteins, GalNAc-T, NG2, CSPG4, ABCB5, MAGEA3, PAX3, TGFB2, TYR2, Human Melanoma Black-45 (HMB-45), Melan-A, tyrosinase, and S100." (PMID 35565234, 2022). "Rather than other stem cell markers, simultaneous expression of ABCB1, ABCB5, and ABCC2 were seen in a subpopulation of melanoma cells." (PMID 35505363, 2022). "Compared with ABCB5, the role of CAV1 in skin diseases is more complex, as expression depends on the type of melanoma." (PMID 36431795, 2022). "In vivo studies in human melanoma proved that different subsets of cells expressing CSC markers (e.g., CD271, ABCB5) were able to recapitulate the heterogeneity of parental tumors when injected into NSG mice." (PMID 35408953, 2022). "The drug efflux transporter ABCB5 (ATP-binding cassette, sub-family B (MDR/TAP member 5) is another controller of IL-8 expression in melanoma cells through a mechanism that involves whey acidic protein 4-disulphide core domain 1 (WFDC1/ps20) and Wnt pathway." (PMID 35011682, 2021). "Among the surface markers commonly used to identify melanoma stem cells are CD133, CD271, ABCB5, and ALDH1A." (PMID 35048028, 2021).